IL1B (interleukin 1 beta)
Diseases named in the same sentence as IL1B in open-access papers (continued):
Sharing a sentence is not in itself a finding about the gene and the disease.
infection (continued). "As shown, both TNFAIP3-KO cell clones (KO#20 and KO#03) showed significant higher levels of proinflammatory factors like TNF-α, IL-6, IL-1β, and CCL2 in response to the infection, as compared to that of the wild-type cells." (PMID 31783671, 2019). "During the course of an infection, the excessive circulating ranges of TNF-α, IL-1β, and IL-6 indicate a rapid array of host responses, such as fever and leukocyte chemotaxis." (PMID 30949497, 2019). "IL-1β secretion upon NLRP3 inflammasome activation initiates acute phase reactions, including the recruitment of inflammatory cells at the site of infection and expression of proinflammatory cytokines, such as, IL-6, TNF-α, and chemokines." (PMID 31590215, 2019). "Herein, a single unilateral injection of EcoHIV (1 × 106 pg) directly into the caudate putamen resulted in a significant increase in inflammatory markers TNFα, IL-1β, IFNγ, CCL2, CCL3 and CXCL10 5 days after infection." (PMID 31263138, 2019). "Inhibition of IL-1β production by IFN-γ has been previously shown in vitro (38, –, 41) and during infection with Mycobacterium tuberculosisin vivo." (PMID 30455194, 2019). "We further investigated soluble proinflammatory cytokines in plasma and lung homogenates (IL-1β, KC/GRO, TNFα, IL-6, IL-12p70, and IFNγ) as well as pulmonary influx of myeloid-derived cells 2 weeks into COXi treatment (week 6 of infection)." (PMID 31396568, 2019). "Here we report the novel finding that within minutes of infection, T. gondii activates a spleen tyrosine kinase (Syk), PKCδ, CARD9/MALT-1, and NF-κB signaling pathway that is critical for the production of IL-1β in primary human monocytes." (PMID 31449558, 2019). "Together, these results indicated that upon infection of HSCs, B. abortus triggers AIM2 and NLRP3 inflammasome activation with concomitant IL-1β secretion in a mechanism that is dependent on a functional T4SS and DNA." (PMID 32038610, 2019). "On the basis of the results, we were led to conclude that the prediction model of three inflammatory factors (IL-8, IL-1β and IFN-γ) had an excellent sensitivity and specificity for the prediction of grade 4–5 infection during the first 30 days after CTI." (PMID 31640816, 2019). "Similar to infection in BMDMs, lungs from coinfected WT mice showed increased production of IL-1β, TNF-α, and IL-6 compared to PR8 or S. p. single infection of WT mice." (PMID 30794604, 2019). "IAV infection increased the mRNA expression at day 3 post-infection (105 PFUs) of IL-6, CCL3, CXCL2, and G-CSF, IL-1β and TNF-α (p < 0.05)." (PMID 30787331, 2019). "Seven days post-infection, the EP birds had remarkably higher expression levels of NF-κB, PPAR-γ, TLR4, and IL-1β (P < 0.05)." (PMID 29948799, 2019). "At the later time point, the infection had minimal if any effect on TNF-α and IL-1β expression in STAT-1-/- and control mice." (PMID 30650607, 2019). "Activation of Rac1 by SopE has been reported to induce caspase-1 activation and IL-1β secretion during S. Typhimurium infection of HeLa or RAW264.7 cells, and in vivo infection of murine enterocytes." (PMID 31402916, 2019). "Compared with blank group, the pro-inflammatory cytokine IL-1β and TNF-α expression levels from other groups were similar, the results demonstrate that the infection of APEC changed from acute period to prognosis." (PMID 31513649, 2019). "The relative expressions of IL-1β, IFN-α, TNF-α, and NF-κB over the course of the infection were detected by qPCR method." (PMID 30760749, 2019). "Since autophagy induction can limit inflammasome activation, we measured IL-1β in the BALF and found a significant decrease in rapamycin-treated mice compared with controls 3 days after infection." (PMID 31031755, 2019). "Going well along with an improved response to infection, SIRT3/5−/− mice had significantly higher blood concentrations of TNF at day 1 (P = 0.001), TNF and IL-1β at day 2 (P = 0.004 and 0.03) and KC/CXCL1 at day 3 (P = 0.05)." (PMID 31632409, 2019).
infection (continued). "Feeding grass carps with SL001-supplemenged diet resulted in a significant increase in expression of IL1β and IL8 at 6 h after infection." (PMID 31316478, 2019). "A single unilateral injection of EcoHIV (1 × 106 pg) directly into the caudate putamen resulted in a significant increase in inflammatory markers (TNFα, IL-1β, IFNγ, CCL2, CCL3, CXCL10) 5 days after infection." (PMID 31263138, 2019). "Meanwhile, the prediction model of three-cytokines (IL-8, IL-1β and IFN-γ) further confirms the diagnosis of grade 4–5 infection." (PMID 31640816, 2019). "Cytokines GM-CSF, GRO-α, I-309, IL-1β, IL-6, MCP-1, MCP-2, TNF-α, thrombopoietin, BLC, Flt-3 ligand, HGF, IP-10, MIF, and MIP-3α were elevated by ≥1.5 fold relative to mock infection in both independent biological replicates of the cytokine array." (PMID 31536604, 2019). "After prior infection, the replication of ARV and the expression of IL-1β were correlated with the development of autophagy in these immune tissues." (PMID 31126305, 2019). "In contrast, infection with less-virulent HSV-1 clinical isolate KOS63 induce less activation of Caspase-1, IL-1β and IL-18." (PMID 31367214, 2019). "Here we further explore the mechanistic basis for NADase-mediated modulation of IL-1β release and find that the expression of functional NADase allows the bacteria to avoid activation of the P2X7 receptor during infection." (PMID 31275321, 2019). "Further, the glycosylated S-layer of T. forsythia ATCC 43037 was shown to suppress the production of proinflammatory mediators IL-1β, TNF-α and IL-8 in U937 macrophages and human gingival fibroblasts, at least at the early stage of infection." (PMID 30842870, 2019). "Upon infection, il-1β:GFP expression was predominantly upregulated in infected macrophages, indicating that within the first 24 h of infection, there is a macrophage proinflammatory response." (PMID 30552162, 2019). "In acute inflammation and infection, leptin levels increase due to the presence of bacterial endotoxins and other signaling cytokines like TNF-a, IL-6, and IL-1b." (PMID 31186010, 2019). "At 4 days after the infection with DENV, blood level of IL-1β and TNF-α mRNA and protein was increased in DENV2-infected mice and DENV2-infected mice treated with IL-1RA but not in mock-infected mice." (PMID 31824450, 2019). "In this paper we showed that macrophages lacking lincRNA-EPS exhibit increased expression of inflammatory cytokines such as TNF-α, IL-6, IL1-β, and CCL5 upon infection with L. monocytogenes." (PMID 32039056, 2019). "Proinflammatory cytokines including IL-1β, IL-6, IL-8, and TNF-α are upregulated and peak at 48 hpi in primary PAMs during infection." (PMID 31363150, 2019). "Release of cytokines, for example, IL-1β and TNF-α, can activate and recruit effector inflammatory cells to the site of infection." (PMID 31998291, 2019). "Infection and ROS activate NF-κB to mediate the expression of NLRP3 and increase the production of pro-IL-1β." (PMID 30779706, 2019). "Similar to WT mice, in the CNS of Rag1−/− mice IFN-α1, IFN-β, TNF, IL-1α, IL-1β, IL-6, and IFN-γ mRNA levels increased following i.c. infection with ZIKV, and IL-2, IL-3, IL-4, and IL-5 mRNA was not detectable (data not shown)." (PMID 31511023, 2019). "High levels of TNF-α, IL-1β, and CXCL10 are present in amniotic fluid from pregnancies complicated by infection compared to uninfected controls." (PMID 31133875, 2019). "Infection of human PBMCs by DENV2(NGC) increased the expression of IL-1β at the mRNA and protein levels." (PMID 31824450, 2019). "Most of these genes, including TNFA, IL1B, IFNG, and IL10, were up-regulated during acute phase of infection and their expression gradually declined, following immunological control the infection, at later stages in Mtb-infected rabbits." (PMID 31382404, 2019). "It is released later in infections compared to inflammatory cytokines, as tumor necrosis factor (TNF)-α and interleukin (IL)-1β." (PMID 31847111, 2019).
infection (continued). "The blood of the mice infected with Δ1717 contained lower concentrations of IL-1β, MCP-1, and TNF-α at 6, 9, and 12 h post-infection." (PMID 31684161, 2019). "Correspondingly, P2X7 inhibition during infections of the human monocytic cell line THP-1, differentiated into adherent macrophages, exhibited similar IL-1β release patterns as BMDMs." (PMID 31275321, 2019). "TNF-α, IL-1β, MPO activity, and epidermal/dermal thickness increased in the infected paw, which confirmed the peripheral inflammation at the primary foci of this infection." (PMID 31138231, 2019). "After infection with the GFP-RFP-LC3 adenovirus, there was fewer red puncta under IL-1β stimulation in chondrocytes; However, AZ3451 treatment cells presented more red puncta." (PMID 31841119, 2019). "Our infection model demonstrated that circulating cytokines TNF, IL-1β, MCP-1, and IFN-γ were largely increased at both 24 and 48 hpi as a severe systemic inflammatory response." (PMID 30837977, 2019). "Thus, examining the production and processing of IL-1β and other cytokines during infection with various live pathogens may unveil new pathways of regulation that could be critical for enhancing or dampening inflammation during different types of infections." (PMID 31449558, 2019). "In the model, an infection leads to activation of immune cells followed by secretion of pro-inflammatory cytokines, e.g. TNF-α, IL-1β, and IL-6." (PMID 31791247, 2019). "Interleukin-1 β (IL-1β), Interleukin-10 (IL-10) and Interferon- γ (IFN-γ) were significantly higher in the first week of infection in mice infected at ZT3 compared to mice infected at ZT15 (p < 0.01, p < 0.01, p < 0.01 respectively)." (PMID 31388084, 2019). "Macrophages in BALF remained markedly high during infection, with concomitant increase in pro-inflammatory cytokines (TNF-α, IL-1β, IFN-γ, and IL-6), compared HAdV-3 infection." (PMID 30626350, 2019). "The inflammatory kinetics of serum in mice at 1, 3, 7 and 11 days after infection by SL1344, CVCC541, and CMCC50115 showed that SL1344 induced significantly high levels of IL-1β, IL-6 and TNFα at 1 and 3 days." (PMID 30898022, 2019). "Infection of IL-10−/− mice with C. jejuni is characterized by increased levels of pro-inflammatory cytokines (TNF-α, IL-1β, IL-6, IFN-γ and IL-22) and infiltration of inflammatory cells in the colon." (PMID 31427597, 2019). "CX3CL1 mRNA expression was also detected in the ipsilateral DRG of infected mice at the 30th day post-infection, and the i.t. injection of TNF-α or IL-1β in naïve animals induced CX3CL1 mRNA expression in the spinal cord and ipsilateral DRG." (PMID 31138231, 2019). "General blockade of IL-1β signaling, like that obtained with FDA approved Anakinra (IL-1R1 antagonist), increases the rate of infections due to the necessity of IL-1β for bacterial infection clearance." (PMID 31244767, 2019). "Samples of paw tissue were collected at day 40 after the infection to evaluate TNF-α and IL-1β production, MPO activity levels, and histopathological analysis." (PMID 31138231, 2019). "In Mtb-infected/Fe-supplemented rabbits, expression of IFNG, TNFA, and IL1B was significantly down-regulated, whereas expression of IL6 and SMAD6 was up-regulated, compared to placebo-treated animals, at 4 weeks post-infection." (PMID 31382404, 2019). "Specifically, during the initial phase of infection, NLRP3 inflammasome is activated to produce IL-1β that promotes the recruitment of neutrophils and the onset of the inflammatory response." (PMID 31681274, 2019). "The use of IL10-targeting siRNA revealed that IL10 inhibited the production of IL1B, IL6, tumour necrosis factor (TNF) and interferon gamma (IFNG) during infection of bMDM with the M. bovis strain G18." (PMID 31527895, 2019). "Although the kinetics of mRNA induction by P. gingivalis differed between individual genes, I-BET151 uniformly reduced IL8, IL1B, CCL2, and CCL5 expression at 4 and 24 h post-infection." (PMID 31114581, 2019).
infection (continued). "In this study, IL-6, IL-1β, and MIP-1α were detected during the later stages of infection when large numbers of PMNs were present." (PMID 31703354, 2019). "Infection with influenza A virus induced the production of IFN-α/β, TNF-α, IL-1β and IL-18 in human peripheral macrophages." (PMID 30717382, 2019). "As expected, infection upregulated the expression of several inflammation-related genes, including TNF-α, IFN-γ, IL-1β, galectin-3, TGFβ, and IL-10, compared to naïve controls." (PMID 31244833, 2019). "For the hub response genes of E. coioides, IL6 and IL1B were induced, while CELA2, TRY, CPA1, CPA2, and CPB1 were repressed throughout the infection process." (PMID 31130962, 2019). "With the infection mouse model above, we found that EDL933(ΔTir + HA-Tir) induced lower Tnf, Il6, Il12b, and Il1b than EDL933ΔTir, which was nearly reversed by EDL933(ΔTir + Y490F, Y519F) in the colons and spleens." (PMID 31130074, 2019). "Following infection with RV43, all groups produced measurable levels of IFN-λ, IL1-β, IL-8, IP-10 and MIP1- α." (PMID 31747925, 2019). "In vitro infection using human THP-1 cells (leukemia cell line) indicated that E. chaffeensis induces upregulation of IL-8, IL-1β, and TNF-α mRNAs as well as the extracellular regulated kinase 2 (ERK2) activation." (PMID 31134081, 2019). "Consistent with increased cellular recruitment, evaluation of lung homogenates showed an overall increase in TNF, IL-1β, IL-6, IL-17 and KC (CXCL1) in Mtb-LT infected mice at four weeks following infection compared with Mtb-HT infected mice." (PMID 30840702, 2019). "Two weeks after challenge infection, group Lipo_DDA:TDB had very high IL-1β levels compared to the other groups." (PMID 31703726, 2019). "Strong production of pro-inflammatory cytokines, including IFNγ, IL-17, IL-1β, and Mip1β, was found in mice immunized with CAF01+H56 24 h after infection by an ELISA assay performed directly on the homogenates of the lungs." (PMID 31130946, 2019). "The pro-inflammatory cytokines IL-6 and IL-1β were strongly induced post-APEC O1-GFP and slightly higher post-APEC O2-GFP infection in macrophages." (PMID 31998322, 2019). "(d) Serum levels of the cytokines IL-1β, IL-10, CCL20 and CXCL2 2 hr after infection by CC17 GBS (n = 9 mice per group)." (PMID 31710290, 2019). "The levels of IL-1β and TNF-α production increased in a multiplicity of infection (MOI)- and time-dependent manner." (PMID 30078841, 2018). "It has been reported that the inflammation is a physiological phenomenon on responding the injury, stress and infection, and the inflammatory mediators of iNOS, COX-2, IL-1β, TNF-α and IL-6 can be increased when ALD occurred clinically." (PMID 29765084, 2018). "In spleen, mRNA expression of IL-1β, IL-6, IL-12, HMBG1, MCP-1, and TGF-β was significantly increased 20 h post-infection, while expression of M-CSF was significantly decreased." (PMID 29755322, 2018). "Over the first 6 weeks after infection, all animals showed similar responses to all strains, although M. tuberculosis BTB1558 generated higher IL-1β responses at day 28 compared to responses induced by M. tuberculosis H37Rv or M. bovis AF2122/97." (PMID 29343690, 2018). "Results from these analyses indicated that GAS induces a 2-fold or greater increase in GM-CSF, IL-1β, IL-6, and MIF in WT vs. mock infection." (PMID 30018884, 2018). "We measured the levels of IL-1β, IL-6, MIP-1α, and CXCL1 in cerebellum and spleen, as well as of bioactive lipids in serum in PEA- and vehicle-treated animals 24 h after infection." (PMID 30505308, 2018). "And infection of macrophages with the three ΔsurA/SCV1, Δslp/SCV1, and ΔlpoB/SCV1 mutants led to significantly decreased expression of TLR2, TNF-α, IL-1β, and IL-6 compared to those detected in the SCVs." (PMID 29594069, 2018). "Macrophages sense B. abortus and induce upregulation of IL-12, IL-1β, TNF-α, and IL-6 genes as early as 30 min after infection." (PMID 29942317, 2018).
infection (continued). "Analyzing the inflammatory response in the lungs, we saw, as expected, an induction of pro- (IL-1β, TNF-α, KC, IL-6) and anti-inflammatory (IL-10) chemo- and cytokines following infection with S. pneumoniae." (PMID 29449834, 2018). "A comparison between MPI cells and BMDM was also performed, showing that 8 h after infection with live bacteria, MPI cells were secreting more TNF-α, comparable amounts of IL-6 and less IL-1β than BMDM, at all the MOI tested." (PMID 29593716, 2018). "After infection of μBS by ZIKV-BR and ZIKV-UG, upregulation of TNF-α, IL6, IL1b, and CCL2 was observed when compared with BS." (PMID 30619100, 2018). "While TNF-α and IL-6 production increased in sole microglia post-infection, CCL2 and IL-1b were upregulated only in μBS." (PMID 30619100, 2018). "IL-1β, TNF-α, or IL-6 present similar patterns of differential expression with a peak at 30 min post-infection when compared with NI cells." (PMID 29942317, 2018). "In contrast, the initial HAM response to infection displays a lag phase with few genes significantly up-regulated at the 2 h post-infection time point (CSF2, IL-1B, IL-6, IL-10, IL-21)." (PMID 29847580, 2018). "Indeed, intradermal infection induced the selective expansion of skin resident Vγ4Vδ1+ and Vγ3Vδ1+ T cell clones with conserved CDR3δ and CDR3γ motifs that were maintained during the convalescent phase and present after secondary infection of WT and Il1b−/− mice." (PMID 30538697, 2018). "Several pro-inflammatory innate cytokines produced by epithelial cells, such as IL-8, IL-1β, IL-12 and TNF-α, were elevated in saliva after infection." (PMID 29621276, 2018). "In M. pneumonia challenged mice, serum IL-6, IL-1β, and TNF-α were significantly higher in mice after 1 month infection than their saline controls." (PMID 29849498, 2018). "Infection with Burkholderia pseudomallei or B. thailandensis triggers activation of the NLRP3 and NLRC4 inflammasomes leading to release of IL-1β and IL-18 and death of infected macrophages by pyroptosis, respectively." (PMID 29791511, 2018). "In early stage infection, TLR3-/- mice showed a diminished synthesis of IFN-β, IL-1β, and IL-6, but enhanced production of IL-10, TNF-α, and IFN-γ." (PMID 29624589, 2018). "In this work, we report that both infection with P. berghei ANKA and gonadectomy triggered a sexually dimorphic cerebral mRNA expression pattern of the cytokines IL-1β, TNF-α, IFN-γ, and IL-2." (PMID 30515051, 2018). "We found in spleens from BALB/c mice 2 days after infection significant amounts of IFN-γ, IL-1α, IL-1β, IL-10, IP-10, and MIG." (PMID 30500862, 2018). "We thus compared the production of IL-1β, IL-17, TNF-α and IL-10 to the number of CFU in the lungs at 96 hours post-infection for each animal." (PMID 29381692, 2018). "Supernatants from PPD-B stimulated samples were also checked for IL-1β, IL-6, IL-10, IL-12, and TNF-α production over the course of infection using the MSD multiplex platform." (PMID 29343690, 2018). "As revealed by pulmonary cytokine detection, the increase in pulmonary TNF-α, IL-1β, IL-6, and IL-8 levels was more severe in the lean mice than in the DIO mice after infection." (PMID 30250258, 2018). "Our findings demonstrate that both infection with P. berghei ANKA and gonadectomy trigger a cerebral sex dimorphic mRNA expression pattern of the cytokines IL-1β, TNF-α, IFN-γ, and IL-2." (PMID 30515051, 2018). "TLR3 deficiency in mice led to increased synthesis of TNF-α, IFN-γ, and IL-10; however, IFN-β, IL-1β, and IL-6 were secreted into the genital tracts of wild-type mice at significantly higher levels than in TLR3-/- mice during early infection." (PMID 29624589, 2018). "Similar observations were made at gene expression level; the infection of Mφs led to a significant increase in TNF-α, IL-1β, and IL-6 mRNA levels, and IL-6 mRNA level was further enhanced with IFN-γ addition (p < 0.01)." (PMID 29503646, 2018).